TEX46 (testis expressed 46)
Description:
Essential for male fertility, sperm head formation and sperm penetration through the egg zona pellucida.
Synonyms: C1orf234; TEX#
Tractability: Antibody: UniProt predicts a signal peptide or a membrane-spanning region.
Gene: Protein-coding gene on chromosome 1 (23,010,834 to 23,019,100, reverse strand). Ensembl gene ENSG00000227868.
Subcellular location: Membrane
Gene Ontology:
Biological process: single fertilization
Cellular component: membrane
Genetic constraint (gnomAD): Loss-of-function variants: 4 observed, 5.42 expected, observed/expected ratio (o/e) 0.74, 90% interval 0.36 to 1.61. That is too few expected variants to judge how well the gene tolerates losing a copy. Missense variants: 131 observed, 157.01 expected, observed/expected ratio (o/e) 0.83, 90% interval 0.72 to 0.96. Synonymous variants: 41 observed, 55.54 expected, observed/expected ratio (o/e) 0.74, 90% interval 0.57 to 0.96.
Homologues: Orthologues: macaque TEX46 (94% identical), chimpanzee TEX46 (83% identical), pig TEX46 (75% identical), dog TEX46 (73% identical), mouse Tex46 (64% identical), rat Tex46 (60% identical).
Diseases named in the same sentence as TEX46 in open-access papers:
TEX46 is named in the same sentence as 11 diseases in open-access papers, as found by Europe PMC text mining. Sharing a sentence is not in itself a finding about the gene and the disease. The quoted sentences say what the papers report.
Infertility (2 papers, 2021 to 2024). "Our findings support a potential role of human TEX46 in sperm function and could be used to develop treatments for infertility (in the case of individuals with mutations in human TEX46) as well as male-specific contraceptives if molecules could disrupt TEX46 function in vivo." (PMID 38516277, 2024). "To uncover if the Tex46 null spermatozoa were infertile due to motility defects, we used a computer-assisted sperm analyzer (CASA) to categorize Tex46 null mouse sperm motility issues." (PMID 38516277, 2024). "However, the major cause of infertility in Tex46−/− mice is not due to impaired sperm motility." (PMID 38516277, 2024).
Globozoospermia (1 paper, 2024). Any structural anomaly of the acrosome resulting in a round sperm head. "Whereas sperm acrosomal membrane protein IZUMO1 in other mice that display globozoospermia is depleted, IZUMO1 levels are normal in this Tex46 null spermatozoa." (PMID 38516277, 2024). "Unfortunately, we could not obtain an antibody for this protein nor TEX46, and thus cannot see the localization and interaction between these proteins and other globozoospermia or acrosome-related genes." (PMID 38516277, 2024). "However, Tex46 null spermatozoa did not have full globozoospermia." (PMID 38516277, 2024). "Thus, Tex46 is neither a globozoospermia-related nor a sperm migration regulating gene." (PMID 38516277, 2024). "Therefore, the phenotype in the Tex46 null spermatozoa is not related to globozoospermia." (PMID 38516277, 2024).
TEX46 also shares sentences with these, for which no sentence is quoted: Azoospermia (1 paper); cancer (1); lung adenocarcinoma (1); lung carcinoma (1); lung squamous cell carcinoma (1); male infertility (1); neuroendocrine disorder (1); Obesity (1); tumor (1).